BRCA1 (BRCA1 DNA repair associated)
Diseases named in the same sentence as BRCA1 in open-access papers (continued):
Sharing a sentence is not in itself a finding about the gene and the disease.
ovarian carcinoma (continued). "The aim of the study was to analyze the prevalence and association of recurrent founder germline mutations in BRCA1, BRCA2, RAD51C, PALB2, and CHEK2 genes with ovarian cancer risk among unselected patients in the Polish population." (PMID 33670479, 2021). "Nevertheless, BRCA1 carriers showed worse DFS, mostly due to higher rates of second primary malignancies (predominantly breast and ovarian cancers) as compared to BRCA2-mutated patients." (PMID 33579978, 2021). "So far, few studies had reported that BRCA1 rearrangement in ovarian cancer was responsive to olaparib." (PMID 33432021, 2021). "Of those not having undergone RRBSO who had follow‐up in the risk period, 15 of 763 (2% age range = 39.7‐72 years; median = 60.6 years; BRCA1 = 12) died from ovarian cancer post genetic testing." (PMID 33152107, 2021). "BRCA1 and BRCA2 (BRCA1/2) gene mutations confer breast and ovarian cancers risks from 35% to 65% and 5% to 50%, respectively." (PMID 31802423, 2021). "Recently, a Phase IIb trial of newly diagnosed patients with stage III/IV ovarian cancer demonstrated greater clinical benefit involving significant advantages in RFS and OS in patients with BRCA1/2 wild-type ovarian cancer." (PMID 34452019, 2021). "Our results are coherent with previous findings showing cisplatin sensitivity in ovarian cancers with low expression of BRCA1." (PMID 33670664, 2021). "The value of BRCA1 and BRCA2 testing for cancer risk reduction in breast and ovarian cancer is well-established." (PMID 34072979, 2021). "Though BRCA1 and BRCA2 are most commonly associated with ovarian cancer as CPGs, several other CPGs have gained attention in recent years." (PMID 34070674, 2021). "Due to its involvement in these functions, defects in BRCA1 are associated with impaired DSB repair and carcinogenesis, particularly breast and ovarian cancer." (PMID 34360968, 2021). "In consideration of the high mutation/deletion rate of the BRCA1 gene in human breast and ovarian cancers, the NBR2 gene, which is proximal to the BRCA1 gene, was initially presumed to be co-deleted/mutated with BRCA1 in certain cancers." (PMID 34926299, 2021). "Germline BRCA1 and BRCA2 mutations have been identified in 14–15% of all ovarian cancers while somatic BRCA1 and BRCA2 mutations are found in 6–7% of high grade serous EOCs." (PMID 33808562, 2021). "Over the past decades, a number of mutations have been identified in hereditary breast cancer, among which BRCA1 and BRCA2 mutations are the most prevalent and associated with increased risk of breast and ovarian cancer." (PMID 34439348, 2021). "We found that a pathogenic mutation in BRCA1, BRCA2, RAD51C or PALB2 was found in 12.51% of unselected cases of ovarian cancer in Poland." (PMID 33670479, 2021). "Overall, 60.7% (564/919) of women with a PV in BRCA1 and a personal history of ovarian cancer were diagnosed after age 50, which is similar to what is seen in the general population." (PMID 33926482, 2021). "There is widespread agreement that all women diagnosed with epithelial ovarian cancers (EOC), with family history of cancer, should be referred for cancer genetic counseling and recommended for germline BRCA1/2 mutations testing." (PMID 33773534, 2021). "Previously, studies have shown BRCA1 IHC is effective method to screen for genetic BRCA1 alterations, and BRCA1 IHC testing has been performed for ovarian cancer with excellent correlation with survival." (PMID 34820332, 2021). "Among patients with ovarian cancer, 8% have BRCA1 mutation, 6% have BRCA2 mutations, 6% have somatic BRCA1/2 mutations, and 10% have BRCA1 promoter inactivation." (PMID 33910165, 2021). "The use of PARP inhibitors has been approved for treatment in BRCA1 and BRCA2 mutated breast and ovarian cancers, and for therapy in platinum sensitive ovarian cancer patients with defective BRCA1/2 genes." (PMID 34639169, 2021).
ovarian carcinoma (continued). "According to investigations, several genes are associated with the pathogenesis of ovarian cancer, and amongst them, two genes—BRCA1 and BRCA2—are well-known ones and found to have significant associations with ovarian cancer." (PMID 33937409, 2021). "ASA-B was presented as the more potent genotoxic agent, including the BRCA1-null ovarian cancer UWB1.289 cells." (PMID 34440232, 2021). "This includes the approval of maintenance therapy with the PARP inhibitor niraparib independent of the biomarker status, or the combined treatment with the PARP inhibitors olaparib and bevacizumab in BRCA1/2‐mutant or HRD‐positive ovarian cancer." (PMID 33738970, 2021). "As an example, the combination of methotrexate (targets folate synthesis) and erlotinib (EGFR inhibitor) in UWB1289 (BRCA1-mutant ovarian carcinoma) cells is antagonistically efficacious and potent by MuSyC, but synergistic by Loewe." (PMID 34326325, 2021). "Previous research has shown that the presence of germline or tumor PVs in BRCA1 or BRCA2 predict benefit from such therapies among women with ovarian cancer." (PMID 33926482, 2021). "The carrier frequency of BRCA1/2 in Chinese NSCLC patients (86/9010 = 0.95 %) was significantly lower than that in Chinese breast and ovary cancer patients (1481/20,523 = 7.2 %) (P < 0.001)." (PMID 33563323, 2021). "Here, we describe a comprehensive clinical testing approach for the assessment of the BRCA1/2 genes in ovarian cancer specimens, which can be used to determine patients’ eligibility for PARP inhibitor therapy." (PMID 32483276, 2020). "The results are consistent with findings from a previous CIMBA study, based on fewer samples and fewer SNPs, which demonstrated that PRS can lead to large differences in absolute risks of developing breast and ovarian cancers for female BRCA1/2 carriers." (PMID 32665703, 2020). "The protein truncating mutations rs397508986 in BRCA1 and rs80358998 in BRCA2, found in the liver and pancreas samples, are components of genetic screening protocols for breast and ovarian cancer." (PMID 33198737, 2020). "The roles of BRCA1 and BRCA2 mutations in chemosensitizing ovarian cancer and improving prognosis are well known, as are the mechanisms by which these can be reversed in development of chemoresistance." (PMID 36046263, 2020). "According to previous studies, blood is a relevant source of RNA for analyses of BRCA1 with respect to breast and ovarian cancer." (PMID 32203205, 2020). "Germline mutations in the tumor suppressor BRCA1 and BRCA2 genes have been strongly associated with an increased risk of breast and ovarian cancer." (PMID 33015058, 2020). "Two important homologous recombination (HR) DNA repair-related genes, BRCA1 and BRCA2 germline mutant confer the genetic predisposition to breast, ovarian cancer and pancreatic cancer." (PMID 33628188, 2020). "The role of BRCA1 in familial breast and ovarian cancer is well documented, but in recent years its importance in several other malignancies has been also discovered." (PMID 32053991, 2020). "Women who carry a pathogenic mutation in BRCA1 or BRCA2 are at increased risk of developing breast and ovarian cancer." (PMID 32772980, 2020). "Giving the high prevalence of positive mutations in BRCA1/BRCA2 genes, it is essential to establish a service for familial breast and ovarian cancer service in Jordan and the MENA region, that includes genetic counselling and early genetic screening." (PMID 33067490, 2020). "PARP inhibitors have been reported as useful tools in triggering the synthetic lethality in a BRCA1- or BRCA2-deficient background of breast and ovarian cancer." (PMID 32900001, 2020).
ovarian carcinoma (continued). "Deficiency has also been shown to sensitize ovarian cancers to PARP inhibitors, demonstrating the case for synthetic lethality of FA proteins other than BRCA1/2 with PARP inhibitor treatment." (PMID 36046263, 2020). "Inherited missense mutations in the enzymatic RING finger domain in both BRCA1 and BARD1 are highly correlated with the occurrence of ovarian cancer." (PMID 33109073, 2020). "An individual carried a pathogenic variant in PMS2 (NM_000535.6) implicated in Lynch syndrome and the two patients carried each a variant in BRCA1 (NM_007300.3) or BRCA2 (NM_000059.3), associated with hereditary breast and ovarian cancer." (PMID 32231684, 2020). "It has been revealed that BRCA1 germline mutation, and HER2 and ER expressions were candidate tumour biomarkers for the risk of breast or ovarian cancer, and for therapeutic assessment of breast and gastric cancers, respectively." (PMID 32598404, 2020). "Somatic reversion mutations and intragenic deletions restoring function of BRCA1 and BRCA2 in patients with known germline BRCA mutations have been well described in chemotherapy-resistant ovarian cancer." (PMID 32403357, 2020). "Most cases of inherited susceptibility to EOC are primarily related to germline mutations of BRCA1 and BRCA2, which account for about 80% of hereditary ovarian cancers." (PMID 32211327, 2020). "All women with ovarian cancer are recommended to undergo germline genetic testing for BRCA1 and BRCA2 (Society for Gynecology Clinical Practice Statement 2014)." (PMID 32403357, 2020). "The term “BRCAness” phenotype was coined to describe sporadic breast and ovarian cancers that behave like hereditary BRCA1/2-related tumors." (PMID 32164626, 2020). "The CIMBA retrospective cohort consisted of 18,935 BRCA1 carriers (9473 diagnosed with breast and 2068 with ovarian cancer) and 12,339 BRCA2 carriers (6332 with breast and 718 with ovarian cancer)." (PMID 32665703, 2020). "For example, cisplatin resistance in ovarian cancer is found to be associated with the re-expression of FANCF228 and the reverse mutation of functional BRCA1 or BRCA2229,230." (PMID 33299637, 2020). "In this study, we performed a sequencing analysis of the BRCA1/2 gene in the second-generation ovarian cancer patients in the selected HOCS family." (PMID 32356124, 2020). "Olaparib (Lynparza) showed activity in individuals with ovarian tumors harboring germ line BRCA1/2 mutations and was FDA approved in 2014 for use in ovarian cancer." (PMID 33376937, 2020). "Traditionally, a threshold of greater than 10% lifetime ovarian cancer risk was used, allowing for RRSO in women carrying BRCA1, BRCA2, or mismatch repair gene mutations, which confer lifetime ovarian cancer risk well in excess of 10%." (PMID 33086730, 2020). "We observed two cases of DH (0.3%) in BRCA1/2 genes in a cohort of 645 probands affected with breast or ovarian cancer." (PMID 33287145, 2020). "While advances in sequencing technology and analysis have improved the detection of BRCA1/2 PVs, testing is uninformative for a number of breast and ovarian cancer cases with high clinical suspicion." (PMID 32884827, 2020). "Signature 3 is closely associated with germline and somatic BRCA1 and BRCA2 mutations in breast, pancreatic, and ovarian cancers." (PMID 32754579, 2020). "Second, considering the family history of patients who were diagnosed with ovarian cancer before 2017, the germline BRCA test was recommended for patients with a high probability of being a BRCA1/2 mutation carrier." (PMID 32131779, 2020). "BRCA1 and BRCA2 are the two well‐known tumor suppressors, and their mutations are associated with increased risk of breast and ovarian cancers." (PMID 32255263, 2020). "Recently, two families with a high breast and ovarian cancer incidence were found to harbor secondary constitutional BRCA1 methylation, also with a methylation level of ~ 50%." (PMID 32859265, 2020).
ovarian carcinoma (continued). "In a familial segregation study of families with breast and ovarian cancer, BRCA1 promoter hypermethylation was present in two out of 49 families, including one proband with triple negative breast cancer and one with HGSOC." (PMID 33396385, 2020). "DNA variants in a number of cancer susceptibility genes are known to be associated with ovarian cancer: women with a high penetrance genetic variant, such as a BRCA1 or BRCA2 mutation, are considered to be at high risk for developing breast and ovarian cancer." (PMID 33260928, 2020). "BRCA1/2 genetic testing offers tremendous opportunities for prevention, diagnosis and treatment of breast and ovarian cancer." (PMID 33031463, 2020). "Women with a BRCA1 or BRCA2 mutation have high lifetime risks of developing breast and ovarian cancers." (PMID 32393849, 2020). "Mutations in BRCA1 and BRCA2 have been recognized as a predictor of advanced-stage ovarian cancer susceptibility and a prognostic factor." (PMID 32131779, 2020). "By analysing large numbers of Chinese hereditary breast and ovarian cancer patients and Caucasian patients, Bhaskaran et al33 recently revealed that germline variations in the BRCA1/2 genes are highly ethnicity‐specific." (PMID 31782247, 2020). "A genome study of ovarian cancer recently revealed that BRCA1 and BRCA2 deficiency, either of which is considered the most important risk factor for hereditary BC and ovarian cancer, lead to different structural changes and mutation patterns in tumor genomes." (PMID 32719318, 2020). "BRCA1 mutation was also reported to be associated with tumor neoantigen production, immune cell invasion, and PDL1 expression in ovarian cancer." (PMID 32607285, 2020). "Among patients meeting criteria for only BRCA1/2, 53.9% of PVs occurred in other breast and/or ovarian cancer genes, 5.2% in Lynch syndrome genes, and 7.8% in other cancer predisposition genes." (PMID 31406321, 2020). "In this study, we evaluated the relationship between BRCA1/2 mutations and CRS and survival outcomes in advanced-stage ovarian cancer patients treated with NAC followed by IDS." (PMID 32131779, 2020). "Women with inherited mutations in BRCA1 or BRCA2 had an increased risk of ovarian cancer, and for BRCA1 or BRCA2 mutation carriers, the lifetime risk of ovarian cancer were 54% and 23%, respectively." (PMID 32096544, 2020). "In BRCA1 and BRCA2-associated hereditary breast and ovarian cancer, cnLOH was reported as the most common LOH mechanism for second hit inactivation." (PMID 33007869, 2020). "Three of the four cases also diagnosed with ovarian cancer in cases were BRCA1/2 heterozygotes: one BRCA1 and two BRCA2 heterozygotes." (PMID 32300229, 2020). "BRCA1 is one of the most common ovarian cancer genes in the process of HR repair of double‐stranded DNA breaks." (PMID 32762026, 2020). "Even though ovarian cancer risk is lower with OC use, it stays elevated and timely risk-reducing BSO is recommended at the age of 40 years for BRCA1 and at the age of 45 years for BRCA2 mutation carriers." (PMID 32140806, 2020). "The carriers of BRCA1 c.5407-25T>A in our study were ascertained from families undergoing genetic testing and counselling for hereditary breast and ovarian cancer." (PMID 32203205, 2020). "Consistent with the promoter hypermethylation, BRCA1 is silenced in sporadic breast and ovarian cancer." (PMID 32269964, 2020). "BRCA1 is a tumor suppressor gene well-known from the pedigree studies of familial breast and ovarian cancers." (PMID 31488892, 2020). "The frequency of BRCA1 and BRCA 2 mutations in ovarian cancer varied greatly in previous reports, ranging from 1.1 to 39.7% and 0 to 13.9%, respectively." (PMID 32856862, 2020).
ovarian carcinoma (continued). "A patient with advanced germline BRCA1 ovarian cancer achieved RECISTv1.1 partial response and Gynecologic Cancer Intergroup CA125 response despite being platinum refractory and PARP inhibitor resistant." (PMID 32568634, 2020). "Pathogenic germline variants in the breast cancer susceptibility genes BRCA1 and BRCA2 increase the risk for the development of ovarian cancer (OC) in carriers." (PMID 32850417, 2020). "Germline and somatic variant testing of the BRCA1 and BRCA2 genes are important to predict treatment response to PARP inhibitors in ovarian cancer patients." (PMID 33008098, 2020). "The OPPS included UWB1.289, an ovarian cancer cell line with a loss of BRCA1 function, and UW1.289 + BRCA1, a cell line engineered from UWB1.289 to restore wild-type BRCA1 function." (PMID 32198459, 2020). "We retrospectively collected and analyzed all clinical information of 1346 hereditary breast and/or ovarian cancer patients genetically tested for germline BRCA1/2 PVs at University Hospital Policlinico “P." (PMID 32380732, 2020). "BRCA1 and BRCA2 are high penetrance genes associated with an increased risk of up to 20-fold for breast and ovarian cancer." (PMID 32039725, 2020). "Most of the breast and ovarian cancer cases in Icelandic families have this BRCA2 founder mutation, while mutations in BRCA1 are very rare." (PMID 33086730, 2020). "Signature 3 is also associated with germline and somatic BRCA1 and BRCA2 mutations in breast, pancreatic, and ovarian cancers." (PMID 32984050, 2020). "Ovarian cancer patients whose tumors have a positive GIS Status and/or pathogenic variants in BRCA1 or BRCA2 are considered good candidates for treatment." (PMID 32403357, 2020). "Sequencing-based genetic tests to screen for mutations in BRCA1 and BRCA2 are recommended to individuals with a personal or family history of early onset and/or bilateral breast and/or ovarian cancer, or a history of male breast cancer." (PMID 33293522, 2020). "In particular, it is estimated to be 3% for carriers of mutations in BRCA1 and 5% to 10% for carriers of mutations in BRCA2, certainly lower than the risk of developing breast or ovarian cancer." (PMID 33198203, 2020). "Together with a preceding report describing the biallelic loss of BRCA1 in a young ovarian cancer patient with multiple congenital abnormalities, this proof contributed to the identification of BRCA1 as FANCS." (PMID 32300589, 2020). "BRCA1/2 sequencing should be considered among the ovarian cancer patients for better clinical management." (PMID 33102229, 2020). "To date, twenty variants in BRCA1, BRCA2, and PALB2 that predispose families to breast and ovarian cancer have been identified as recurring in the French-Canadian founder population." (PMID 32300229, 2020). "As such, proliferating BRCA1 mutant ovarian cancer cells are typically sensitive to PARPi and treatment can result in a rapid lethal accumulation DNA DSB." (PMID 32098452, 2020). "Classification of variants in the BRCA1 and BRCA2 genes has a major impact on the clinical management of subjects at high risk for breast and ovarian cancer." (PMID 32814805, 2020). "The prevalence and penetrance of deleterious variants in BRCA1 and BRCA2 has been extensively studied in ovarian cancer patients." (PMID 33086730, 2020). "NBN overexpression in breast and ovarian cancer cells leads to BRCA1-dependent olaparib resistance by promoting the phosphorylation of ATM-S1981 and homology-dependent recombination efficiency." (PMID 32226530, 2020). "Both came for BRCA1/2 testing after one was diagnosed with triple negative breast cancer and the other had ovarian cancer." (PMID 32778078, 2020). "DNA damage or DNA repair defects caused by BRCA or ERCC1 mutations can also activate this pathway and thereby potentiate PARP inhibitor effects in ERCC1-deficient nonsmall cell lung cancer, BRCA1-deficient TNBC, and ovarian cancer." (PMID 32029455, 2020).